RNU6-549P (RNA, U6 small nuclear 549, pseudogene)
Gene: Small nuclear RNA gene on chromosome 15 (64,671,263 to 64,671,369, forward strand). Ensembl gene ENSG00000207162.
Homologues: Orthologues: chimpanzee U6 (100% identical), macaque U6 (91% identical), dog U6 (85% identical), rabbit U6 (78% identical). Paralogues in human: RNU6-20P (88% identical), RNU6-476P (88% identical), RNU6-48P (88% identical), RNU6-641P (88% identical), RNU6-1158P (87% identical), RNU6-1263P (87% identical), RNU6-21P (87% identical), RNU6-25P (87% identical), RNU6-33P (87% identical), RNU6-38P (87% identical), RNU6-468P (87% identical), RNU6-574P (87% identical), and 1289 more.